TNF (tumor necrosis factor)
Diseases named in the same sentence as TNF in open-access papers (continued):
Sharing a sentence is not in itself a finding about the gene and the disease.
Obesity (continued). "Moreover, the link between obesity-induced ER stress and chronic inflammation was confirmed by a notably increase in TNFα mRNA levels and macrophages infiltration in adipose tissue of obese mice." (PMID 33805912, 2021). "Changes in the production of adipokines such as leptin, resistin, lipocalin 2, tumor necrosis factor-α, chemerin, retinol binding protein 4, and interleukin-6 have been reported in obese individuals, and this can lead to the development of obesity-related metabolic diseases." (PMID 33498329, 2021). "Stimulation of the TLR signalling pathway, particularly TLR4 in obesity-induced inflammation by LPS in PBMCs may lead to increase pro-inflammatory cytokine production such as TNF-α and NF-κB." (PMID 34835958, 2021). "A significant correlation between liver dysfunction (AST, ALAT, TBIL, and prothrombin time) and inflammatory cytokines was solely observed in patients with obesity suggesting a preexisting liver abnormalities/sensitivity to cytokines such as TNFα involved in many forms of liver injury." (PMID 34038475, 2021). "Chronic inflammation, marked by raised serum interleukin 6 (IL-6), C-reactive protein (CRP) and tumor necrosis factor alpha (TNF-α), anemia and lower hematocrit levels, immune activation, as well as obesity and other comorbidities have also been defined as etiologies of frailty." (PMID 34574503, 2021). "Pathologically, Firmicutes could induce obesity and hepatic steatosis and promoted the elevation of TNF-α mRNA levels, suggesting that Firmicutes might be involved in the pathogenesis of the nonalcoholic fatty liver disease (NAFLD)." (PMID 34592890, 2021). "In obesity, the adipose tissue often takes on dysfunctional paracrine and endocrine roles, marked by chronic secretion of pro-inflammatory adipokines, including TNFα." (PMID 34576943, 2021). "Furthermore, the elevated TNF-α levels can reduce the lipid oxidation and increase the lipid accumulation, leading to obesity." (PMID 34574191, 2021). "TNF-related publications have supported that obesity is an inflammatory process." (PMID 33805313, 2021). "Moreover, IL-6 and TNF-α, which are elevated during obesity, have been shown to promote osteoclast differentiation, thereby prompting bone loss." (PMID 33554957, 2021). "Thus, inhibition (or an inhibitor) of TNF-α-induced COX-2 expression in (pre)adipocytes is considered as a potential target in alleviating obesity inflammation." (PMID 34063048, 2021). "During obesity, an increase in adipocyte size correlates with a greater release of TNF." (PMID 34834553, 2021). "There is a well-recognised link between TNF-α, obesity, inflammation, and diabetes." (PMID 35008648, 2021). "Obesity in DM promotes elevated levels of pro-inflammatory factors such as tumor necrosis factor-alpha (TNF-α) and interleukin-6 and decreases the levels of adiponectin with anti-inflammatory actions, resulting in chronic inflammation, which can promote hepatocarcinogenesis." (PMID 34831299, 2021). "In general, GF mice are resistant to HFD-induced obesity, produce lower levels of inflammatory cytokines including TNFα, IFNγ, IL-1B, and IL-17, and have blunted transcriptional oscillations of the core clock gene Bmal1 relative to conventionally-raised specific pathogen-free (SPF) mice." (PMID 33255707, 2020). "This suggests that TNF-α needs further investigation to explore if it has a role in monitoring the effectiveness of management in individuals with obesity and T2DM.α) is a cytokine that is released by adipocytes and inflammatory cells in response to chronic inflammation." (PMID 32089876, 2020). "The interaction among obstructive sleep apnea syndrome (OSAS) severity, sex, and obesity on cardiovascular risk as determined by serum levels of C-reactive protein (CRP), interleukin-6 (IL-6), and tumor necrosis factor-α (TNF-α) remains unclear." (PMID 32629899, 2020). "TNF-alpha production is also increased in obesity and correlates with the IL-17 production." (PMID 32587472, 2020).
Obesity (continued). "It is clear that obesity induces low-grade chronic inflammation (hereafter referred to as “metaflammation”) by increasing the release of pro-inflammatory cytokines, including tumor necrosis factor-α (TNF-α), leptin, and adipose tissue-derived resistin." (PMID 33110180, 2020). "In addition, obesity as well T2DM, are associated with increased inflammatory cytokines, such as TNF- α and IL-6 which have been shown to lead to osteoblast dysfunction." (PMID 33537005, 2020). "The mechanisms of adiponectin downregulation in obesity are not fully understood, but it may be related to adipose tissue macrophage secretion of Tumor Necrosis Factor Alpha (TNFα) and oxidative stress suppressing adiponectin gene expression." (PMID 33122755, 2020). "Cytokines are closely related to obesity, such as resistin, leptin, adiponectin, and TNF-α." (PMID 32439940, 2020). "In addition, the consumption of green tea reduced the imbalanced production of cytokines such as TNF-α, IL-1β, and IL-6 in the cortex, cerebellum, and brainstem in obesity-induced mice." (PMID 33312340, 2020). "Moreover, inflammatory markers that allow monitoring of obesity and MetS include proinflammatory cytokines production such as TNF-α, IL-1β, and IL-6, which are mainly produced by the macrophages infiltration induced by obesity in the adipose tissue." (PMID 32178436, 2020). "Its downstream signaling pathway may be attenuated in obesity by chronic exposure to TNF-α through NF-κB-mediated upregulation of IKKε and TBK1, which inhibit cAMP signaling via phosphodiesterase 3B." (PMID 32604889, 2020). "Though recent studies have shown an increase in TNF-α and IL-6 levels due to the state of inflammation related to overweight and obesity, the consumption of 60 g/day of cheese, following a balanced and hypocaloric diet, kept these levels stable at the end of the intervention period." (PMID 32380746, 2020). "The effect of burns and obesity on the relative expression of TNF- and VEGF gene in wounds." (PMID 33354433, 2020). "In particular, for the first time, we demonstrated that 4-HIL could suppress TNF-α production by reducing the expressions of iRhom2, which have been proved to be promising targets of obesity-related metabolic diseases." (PMID 33298044, 2020). "In addition, increased expression of TNF-α has been observed in adipose tissue in various obesity models in rodents." (PMID 33322719, 2020). "Metabolic NAFLD complications, obesity, insulin resistance and type 2 diabetes involve a chronic “low-grade inflammation”, resulting in the increase in obesity-related inflammatory molecules, such as: TNF-alpha, IL-1beta, IL-6, IL-1Ra, and C-reactive protein (CRP)." (PMID 33306695, 2020). "Furthermore, the adipose tissue of patients with metabolic syndrome and obesity produces inflammatory cytokines, particularly tumor necrosis factor (TNF) and interleukin-6 (IL-6)." (PMID 33143256, 2020). "Accumulating evidence suggests that TNFα plays an important role in the dysregulation of macrovascular and microvascular function in metabolic and inflammatory diseases, such as obesity, diabetic metabolic syndrome, myocardial ischemia/reperfusion, and rheumatoid arthritis." (PMID 32190663, 2020). "Obesity may be accentuated by TNF inhibition, at least to a moderate degree, but this drug class favors visceral adiposity." (PMID 32183053, 2020). "Additionally, Blautia has been described to exhibit closely positive correlation with TG, TC, IL-6, TNF-α and IL-1β, linking to hepatic lipogenesis and obesity." (PMID 33390939, 2020). "Thus, it is likely that stearic acid plays a role in the TNF-α mediated induction of inflammatory marker MIP-1α/CCL3 in the settings of obesity." (PMID 33050324, 2020). "The chronic low-grade inflammation associated with obesity also contributes to excessive release of lipids by adipocytes, as the inflammatory cytokine TNFα can also induce lipolysis in a manner independent of insulin signalling." (PMID 33292104, 2020).
Obesity (continued). "Furthermore, there are multiple factors, particular obesity, increase the levels of adipocytes, inflammatory cytokines (IL-1, IL-6, and TNFα)." (PMID 32982969, 2020). "However, ST2 deficiency did cause significant reductions in serum IL-1β, TNFα, and CCL5 in the HFD-fed mice, suggesting that IL-33 contributes to aspects of the systemic inflammation of obesity." (PMID 32326950, 2020). "The downregulation of the in vivo IRS1 levels could be due to other molecules, such as TNFα, glucocorticoid and mineralocorticoid, which are increased in obesity." (PMID 32806641, 2020). "The first evidence linking inflammation to metabolic health dates back to 1993 when Gokhan Hotamisligil and Bruce Spiegelman discovered the increasing expression of pro-inflammatory cytokine tumor necrosis factor (TNF)-α in adipose tissue (AT) of rodent models of obesity." (PMID 32140136, 2020). "Obesity has been associated with circulating inflammatory biomarkers, including higher concentrations of leptin, C-reactive protein (CRP), interleukin (IL)-6, and tumor necrosis factor-α (TNFα), and lower adiponectin." (PMID 33259491, 2020). "In obesity, adiponectin levels are found to be reduced, given that its expression is inhibited by hypoxia, oxidative stress, insulin resistance, TNF-α, IL-6, “catecholamine resistance”, fetuin A, and SeP." (PMID 32604889, 2020). "TNF-α and IL-6 secreted by adipocytes up-regulates PD-L1 in hepatoma and B16-F1 cells, which may be at least partially involved in the role of obesity in promoting tumor progression." (PMID 32477009, 2020). "Furthermore, TNF is a core substance in the expression of obesity-related insulin resistance, as it promotes insulin resistance by reducing the tyrosine phosphorylation of insulin receptors in muscular and adipose tissues." (PMID 33133214, 2020). "In addition, EAT obtained from subjects with obesity tend to present higher levels of IL-6 and TNF-α, cytokines abundantly secreted in COVID-19 patients." (PMID 32849309, 2020). "Expression of TNF-α and IL-6 are increased in obesity and insulin resistance." (PMID 32796637, 2020). "Moreover, TNF-α has been shown to play an important role in endothelial dysfunction during obesity and metabolic diseases." (PMID 32907629, 2020). "In addition, no inhibitory effect was observed after stimulation with cytokines TNFα and IFNγ, which are both elevated in obesity." (PMID 32849273, 2020). "In obesity, the white adipose tissue produces large numbers of inflammatory agents including TNF-α and IL-6, which can affect the physiology of the adipose tissue locally, but also may induce systemic effects on the other organs." (PMID 32555600, 2020). "In obesity, the recruitment of macrophages to the expanding adipose depots can induce an inflammatory state characterized by increased expression and secretion of inflammatory cytokines such as TNF-α, IL-6, and IL-1β." (PMID 33072120, 2020). "While increased IFNγ secretion by NK cells drives metabolic dysfunction during early-stage obesity, TNFα secretion by NK cells may play a larger role in driving inflammation and metabolic dysfunction during chronic obesity." (PMID 32499756, 2020). "Indeed, in several rodent models of obesity, TNF-alpha expression in adipose tissue was upregulated as compared with controls." (PMID 33306695, 2020). "Recent studies suggest that diet-induced obesity alone may reprogram skeletal muscle to increase the production of inflammatory cytokines, including TNFα, MCP1, and IL-1β." (PMID 32316567, 2020). "The TNF-α mRNA induction also directly preceded obesity onset in these animals." (PMID 31936158, 2020). "In research studies about obesity, acupuncture could regulate inflammatory cytokines, such as TNF-α, IL-6, and IL-1β and inflammatory cells, such as macrophages." (PMID 32595736, 2020).
Obesity (continued). "The mRNA levels of obesity-related inflammation genes like F4/80, TNFα, CD11c, MCP1 and IL6 were lower in these SOD3-administered mice and hepatic de novo lipogenesis genes like SREBP1c, fatty acid synthase and Scd1 were higher in mice that were just given a high fat diet." (PMID 32903449, 2020). "However, adipocytokine secretion is strongly influenced by obesity, with higher TNF-α, IL-6 and leptin and lower adiponectin levels in adipocytes from morbidly obese subjects than from non-obese subjects." (PMID 32244787, 2020). "Generally, obesity is defined as a state of chronic inflammation, which is characterized by the constant over-production and release of pro-inflammatory adipocytokines, like leptin, resistin, visfatin as well as tumor necrosis factor alpha (TNF-α)." (PMID 32943048, 2020). "Obesity and in particular central adiposity – the excess deposition of visceral fat – is associated with increased serum levels of pro-inflammatory cytokines such as interleukin 6 (IL-6), C-reactive protein (CRP), and tumor necrosis factor (TNF)." (PMID 32508807, 2020). "Thus, inflammatory adipokines such as NOV, TNF-α, and IL-6 have emerged as key regulators of obesity and insulin resistance." (PMID 32751794, 2020). "In addition, work in mice found that Bacteroides uniformis improves immune defense mechanisms, which are impaired in obesity, by decreasing TNF-α production and increasing IL-10 production." (PMID 32917289, 2020). "Recent in vivo studies in models of obesity and human studies have indicated that αT supplementation was capable of attenuating inflammatory processes by reducing the expression of IL-6, TNF-α, malondialdehyde and C reactive protein while increasing antioxidant constituents." (PMID 32903449, 2020). "Thus, the downregulation of Il6 and TNFα secretion by V. opulus is relevant not only for bone metabolism but it also has an impact on obesity state, contributing to osteoporosis delay." (PMID 32664580, 2020). "Moreover, TNF-αnull mice were protected from obesity-induced reduced number of taste bud cells, and administration of exogenous TNF-α brought back taste buds to degeneration." (PMID 32650509, 2020). "Obesity can trigger an immune response by producing cytokines such as tumor necrosis factor α (TNF-α), IL-6, and IL-1, initiating an acute immune response, further suggesting the possibility to induce inflammatory responses inducing a progression of periodontal disease." (PMID 32344600, 2020). "TNF-α and IL-6 have been proposed as a link between obesity and insulin resistance." (PMID 32911750, 2020). "In obesity there is constant macrophage infiltration into adipose tissue and changes in the local production of pro-inflammatory cytokines such as interleukin 1 and 6 (IL-1, IL-6) and tumor necrosis factor α (TNFα)." (PMID 32752277, 2020). "In the persistently slight inflammation situation induced by obesity and liver fat infiltration, the concentrations of inflammatory adipokines such as TNF-α and IL-6 increased and aggravated IR further, while simultaneously caused the inhibition of ADP production and secretion." (PMID 32054179, 2020). "The level of IL-6, TNF-α, and other pro-inflammatory mediators were elevated in obesity people." (PMID 32596152, 2020). "In experimental animal models of obesity, TNF-a expression is increased in adipose tissues." (PMID 32598403, 2020). "Therefore, TNFα systemic levels would also be reduced by EPA indirectly through NFkB regulation in our obesity model." (PMID 32906847, 2020). "Indeed, in the early stage of obesity, neutrophils infiltrating adipose tissue lead to release of different substances like free radicals, TNF-α, and MPO." (PMID 32963689, 2020). "Some mechanisms that are triggered by obesity involve the inflammatory process, which includes the production of proinflammatory cytokines such as interleukin-6 (IL-6) and tumor necrosis factor-α (TNF-α)." (PMID 32795274, 2020).
Obesity (continued). "Macrophage secreted-adipokines such as TNF-α and IL-6 can induce low grade inflammation; thus, obesity could lead to insulin resistance (IR), increased leptin, and decreased adiponectin." (PMID 32961822, 2020). "Leptin may upregulate the production of inflammatory cytokines such as CRP, TNF-α, IL-6, and IL-12 and be involved in low-grade inflammation, which plays a central role in the pathophysiology of obesity, depression, metabolic and cardiovascular disease." (PMID 33036196, 2020). "This increase in KIR2DS1 promoted an increase in TNF-α production, indicating that obesity in some way programs uNKs to acquire pro-inflammatory characteristics that may initiate or drive cellular changes within the uterus." (PMID 32471078, 2020). "Stearic acid levels along with TNF-α are increased in the plasma of individuals with obesity." (PMID 33050324, 2020). "Furthermore, obesity is known to decrease the response rate to TNF-α inhibitors in patients with RA." (PMID 32276645, 2020). "A long period of EGCG treatment reduced obesity development, and symptoms related to metabolic diseases and fatty liver through reduced lipid absorption and decreased inflammatory cytokines such as TNF-α, IL-1β, and IL-6." (PMID 32641048, 2020). "Another study showed that accumulation of inflammatory cells and adipocytes results in increased secretion of cytokines like tumor necrosis factor alpha (TNF-α) and interleukin-6 (IL-6) and lead to the progression of metabolic syndrome, consequently worsening the outcome of obesity." (PMID 33042134, 2020). "In obesity, it can directly or indirectly affect immune tolerance by altering the secretion of adipokines (mainly leptin, adiponectin, and mucin) and/or cytokines (interleukin-6, tumor necrosis factor alpha, and interleukin)." (PMID 32256575, 2020). "TNF-α is recognized as a major culprit in the chronic low-grade inflammatory state of obesity." (PMID 33298044, 2020). "Other studies have also demonstrated that the development of obesity increases the secretions of various pro-inflammatory chemokines and cytokines from adipose tissues, such as tumor necrosis factor-alpha (TNF-α), interleukin-1beta (IL-1β), IL-6 and monocyte chemoattractant protein-1 (MCP-1)." (PMID 32143330, 2020). "Myeloid-specific deletion of three clusters of miR-17~92 family miRNAs twisted ATMs toward a spontaneously inflammatory phenotype characterized by diminished IL-10 and elevated TNF, leading to disrupted adipose homeostasis evidenced by obesity and compromised glucose tolerance." (PMID 33150865, 2020). "However, many studies have shown that in obese AT, the mRNA levels of TNFα and its protein increase, and there is controversy about the relationship between obesity and TNFα concentration." (PMID 33278072, 2020). "Obesity, as a characteristic of metabolic syndrome, is related to chronic low-grade inflammation in obese subjects, because of various pro- and anti-inflammatory cytokines produced by adipose tissues, including IL-6, TNF-α, CCL2, PAI-1, and others." (PMID 32486076, 2020). "Furthermore, phloretin significantly reduced TNF-α levels in the serum of mice with HFD-induced obesity." (PMID 33014333, 2020). "Hence, our results showed that with obesity triggered dysmetabolism, hyperglycemia and hypertriglyceridemia, as well as an increase of the levels of inflammatory cytokines (TNF-α, IL-6), are present." (PMID 32795274, 2020). "Furthermore, a study in 446 children (aged 6–12 years) found that TNF-α, IL-6, and IL-8 increased in children with obesity compared to the NW group and that inflammation and anthropometric and metabolic features are independent risk factors for CVD." (PMID 33299523, 2020).